NRAS (NRAS proto-oncogene, GTPase)
Diseases named in the same sentence as NRAS in open-access papers (continued):
Sharing a sentence is not in itself a finding about the gene and the disease.
tumor (continued). "An important question is whether MAP2K1-driven tumours align with conventional WHO melanomagenesis pathways, alongside BRAF, NRAS, and NF1 mutations, or pathway IV (Spitz), alongside kinase gene fusions and HRAS mutations." (PMID 40107205, 2025). "The tumor was KRAS, NRAS, and BRAF WT, and tumor mutational burden was 4 Mut/Mb." (PMID 41171165, 2025). "The tumor was KRAS, NRAS, and BRAF WT, and the tumor mutational burden was 6 Mut/Mb." (PMID 41171165, 2025). "The benefit provided by EGFR mAbs in KRAS WT mCRC is associated with left-sided primary tumour location, younger patient age and absence of NRAS or BRAF mutations." (PMID 38402342, 2024). "Similarly, data for 60 CRC patients regarding NRAS and BRAF mutation status were available showing that only 10% and 5% of these tumours presented mutations respectively." (PMID 38566765, 2024). "A recent retrospective review of the AACR genie, a clinico-genomic database showed that co-occurring MAPK-pathway mutations (e.g., NRAS, NF1) are significantly more likely with class-1 MAP2K1-mutations (82.3%) compared to class-2 (30.9%) and class-3 (10.6%) in any tumor type." (PMID 39314226, 2024). "It is possible that a tumor cell clone lacking the NRAS p.G12D mutation was responsible for the relapse in this patient." (PMID 38339300, 2024). "Next, we assessed the ability of Mb24 to inhibit NRAS-mutant human tumor cells." (PMID 39379700, 2024). "Sensitivity of NRAS Q61-mutant tumours to MEK inhibitors has also been shown clinically." (PMID 39372214, 2024). "Furthermore, we have previously shown in mice that SKP2 overexpression alone is not sufficient to induce malignant liver transformation, but it cooperates with oncogenic NRAS (NRASV12) to induce tumor development." (PMID 39064589, 2024). "Tumor genetics, particularly mutations in the v-raf murine sarcoma viral oncogene homolog B1 (BRAF), Neuroblastoma Ras viral oncogene homolog (NRAS), and receptor tyrosine kinase proto-oncogene (c-KIT) genes, can impact how effectively T-VEC targets and destroys cancer cells." (PMID 39429342, 2024). "The analysis showed that the tumor harbored an NRAS codon 61 mutation, but no other coding alterations were covered by our clinical panel." (PMID 39363120, 2024). "Moreover, as confirmed for SN-MM3 CDX cells, they also share the molecular driver NRAS p.Gly12Asp with the corresponding parental tumor and cell line." (PMID 38191367, 2024). "Therefore, the observed associations between the expressions of the SEMA7A, SEMA4D, ADAM8, and ADAMTS10 in tumor groups with KRAS, NRAS, BRAF, PIK3CA, and AKT mutations require validation in larger study cohorts." (PMID 39329961, 2024). "Ex-vivo comparison of the NRas Q61R and NRas G12D mutants in allelic knock-in mice revealed NRas Q61R was significantly more tumour-promoting and showed a significantly lower in rate of nucleotide exchange, with a stronger propensity to remain in its GTP-bound state." (PMID 39372214, 2024). "Molecularly, all tumor models exhibit common driver mutations in CTNNB1 and AXIN1, with TLCT models showing the characteristic TERT mutation, and some models progression-associated alterations in the NFE2L2 and NRAS genes." (PMID 39529166, 2024). "As MNAC is an HPV-independent neoplasm, it follows a distinct pathophysiology and has been linked to several genetic mutations, including KRAS/NRAS, ARID1A, ARID1B, SMARCA4, and CTNNB1 mutations, along with chromosomal alterations such as gains of 1q, chromosomes 10 and 12, and loss of 1p." (PMID 39797200, 2024).
tumor (continued). "Higher phosphorylated mTOR expression was associated with the absence of a tumor capsule, the presence of distant metastases, the persistence of disease, and NRAS mutation." (PMID 36980552, 2023). "Our analysis highlights that ASCETIC consistently identifies alterations in CALR, JAK2, and IDH1/2 genes as early events in tumor history, while NRAS represents an acquired secondary event, towards which evolutionary trajectories appear to converge during the progression of the disease." (PMID 37749078, 2023). "In addition, molecular pathology analysis of the original tumor was performed in Germany for the detection of predictable genetic alterations such as BRAFV600E and NRAS gene mutations." (PMID 38115146, 2023). "mRNA levels of RASs (KRAS, HRAS, and NRAS) in LUAD patients with different tumor stages." (PMID 38206735, 2023). "Furthermore, the correlation between BRAF, KRAS, NRAS mutations, and FAP and CXCR4 in both the primary tumor and the first metastasis were examined." (PMID 37892020, 2023). "On the contrary, in a functional study that employed a pooled in vivo screen, Y64D mutant did not promote tumor formation, and it induced a gene expression profile in culture close to the signature of the wild-type NRAS allele." (PMID 37841434, 2023). "Two patients showed NRAS mutations in the plasma, but not in their tumor biopsy sample, while only one patient showed such a discrepancy for BRAF gene mutations." (PMID 37176143, 2023). "One possible explanation for this observation is that the observed correlation could reflect a more complex interplay between MALAT1 and NRAS expression in the tumor microenvironment, which cannot be recapitulated in vitro using cell lines." (PMID 37235843, 2023). "NRAS mutations are also commonly found in conjunctival nevi; however, it remains unknown whether there is a link between the NRAS status and tumor origin in CM." (PMID 37761808, 2023). "BRAFV600E mutation was positive in the tumor samples while no alteration in the NRAS gene was observed." (PMID 38115146, 2023). "Given the ability of H/K/NRAS to form productive complexes with SHOC2–PP1C and the fact that they are frequently mutated in cancers, we explored the co-requirement of RAS and SHOC2 for cell fitness in an extensive panel of tumour cell lines." (PMID 35768504, 2022). "First of all, studies have shown that NRAS upregulation is another resistance mechanism of BRAF inhibitors and NRAS upregulation may promote the dimerization of RAF, which will cause insensitivity of ERK signaling to drugs, leading to tumor drug resistance." (PMID 35912223, 2022). "Inconsistently, NRAS and BRAF in the context of oncogenic, which gain new and tumour-related cellular functions because of nucleotide mutations, MITF turn into oncogenic by deregulating, impacting survival systems that are also described in the general melanocyte lineage." (PMID 36551688, 2022). "NRAS expression is remarkably increased in RB tissues and cell lines, and silencing NRAS with a small interfering RNA (siRNA) markedly suppressed the proliferation, migration, and invasion of RB cells in vitro and repressed the tumor growth in vivo." (PMID 35339759, 2022). "A distinct profile of NRAS mutants is observed in each tumor type." (PMID 35672316, 2022).
tumor (continued). "Through GSEA enrichment analysis, we also observed that low PAQR5 gene expression was associated with upregulation of STAT3 targeting, downregulation of tumor metastasis, upregulation of tumor formation, poorer tumor differentiation, and downregulation of the NRAS signaling pathway." (PMID 36119517, 2022). "The factors that determine the distinct profiles of NRAS mutants across different tumor types remain unclear." (PMID 35672316, 2022). "Moreover, we elucidated the potential mechanism by which circRanGAP1 accelerates the HCC progression by modulating the miR-27b-3p/NRAS/ERK axis and influencing the infiltration levels of tumor-associated macrophages." (PMID 36348379, 2022). "Here, we took advantage of the whole-genome CRISPR knock-out screening to analyze whether, several genes involved in ferroptosis are differentially required in tumor cells having mutations in the RAS genes (KRAS, NRAS and HRAS) and those harboring KRAS-WT." (PMID 35912247, 2022). "Among the 17 studies, 13 (76.5%) used FFPE tumor samples for KRAS, NRAS and BRAF mutation analysis." (PMID 36344948, 2022). "Primary tumors and tumor recurrences or metastases of these three patients before and after radiotherapy were sequenced, whereas no emerging NRAS mutation was detected." (PMID 34072863, 2021). "Also, here a unifying picture captures additional aspects of the tumor evolution with a MYCN-amplification in the stem and a subclonal NRAS mutation." (PMID 34545199, 2021). "The tumor of patient 2 revealed a high proportion of KRAS p.G12A mutated cells (64.2%), concordant with our previous results and reflecting an amplification of the mutant allele, but no NRAS mutation (tumor cell content of the whole section: 70%)." (PMID 34072863, 2021). "Therefore, we only analyzed patients who were refractory or intolerant to standard chemotherapies [FU, OX, IRI, bevacizumab, and anti-EGFR antibody (if the patients had wild type KRAS/ NRAS tumor)] in order to minimalize the inherent bias." (PMID 33763345, 2021). "It was also unable to compare the prognostic performance of vascular-metabolic profiles to well-known pathological risk factors such as tumour regression score, circumferential resection margin, lymphovascular/perineural invasion, microsatellite instability, KRAS, NRAS, BRAF mutations." (PMID 33837843, 2021). "However, the most clinically actionable mutations for this tumour type (BRAF and NRAS) were found to be concordant." (PMID 33435284, 2021). "Through analyses of a variety of human KRAS, NRAS or BRAF mutant cell lines from different tumor entities (CRC, NSCLC, PDAC, RMS) we further showed that these principles also apply to the complex genetic backgrounds that arise during human RAS-pathway driven cancer development." (PMID 33924486, 2021). "In summary, NRAS mutant tumors of the initially responding patients showed a slightly higher CD8+ accumulation in the tumor and at its margins, while the NRAS mutant tumor of the intrinsic resistant patient showed a decreased infiltration compared to the WT tumors." (PMID 34072863, 2021). "In the present study, of 60 PTCs, 41 were BRAF-mutated (68.3%) and TERT promoter-mutated (3.5%), in contrast to no NRAS or KRAS mutation in the tumor tissues." (PMID 33915745, 2021). "Interestingly, other comutant alterations included additional alterations in NRAS in 1 tumor, a rare A18T mutation (7.1%); PIK3CA in 2 tumors (16.7%); and EGFR in 1 tumor, also a rare D761N mutation (7.1%)." (PMID 34063999, 2021). "Recent data show that NRAS is strongly dependent on ICMT activity for efficient trafficking, which would suggest that ICMT inhibitors could be a good therapeutic strategy for NRAS-driven tumours." (PMID 34200676, 2021).
tumor (continued). "Therefore, identical variants present in the genomic DNA of tumor cells, such as mutations in KRAS, NRAS, BRAF, and other genes, can be identified in ctDNA." (PMID 33919272, 2021). "There were no KRAS or NRAS mutations with indices higher than the cut-off values in DNA purified from pretreated primary tumor cells." (PMID 34840814, 2021). "Another similar study showed that regardless of the mutation prevalence, BRAF, and NRAS mutations are not necessary for melano-cytic tumor development." (PMID 34567185, 2021). "MAPK and NRAS were found to be highly expressed in our study, suggesting residual tumor activity." (PMID 34638557, 2021). "The available tumor genotyping data showed mutation of KRAS for 16/43, mutation of NRAS for 3/29, NRAS unknown status for 14/43, mutation of BRAF for 5/35, and BRAF unknown status for 8/43." (PMID 33934494, 2021). "Our studies expanded on this data, showing enhanced tumor regression in response to trametinib in an MYCN non-amplified NRAS-mutated SK-N-AS xenograft when YAP is genetically knocked down." (PMID 34572875, 2021). "One is that the proportion of pheomelanin in NRAS mutant tumors (11.67% in the control tumors) is clearly higher than that in the B16BL6 tumor (1.61%), which could considerably increase TRT-induced oxidative stress." (PMID 33804655, 2021). "The tumor of patient 1 revealed the previously detected KRAS p.G12R mutation (frequency: 4.6%), confirmed the NRAS p.Q61R mutation, previously detected using the corresponding antibody (frequency: 3.3%), and revealed an additional NRAS p.G12V mutation (frequency: 7.0%)." (PMID 34072863, 2021). "The best compound 3144 was tested against a number of different cell lines with WT and mutant NRAS (G13D, G13V), and selective inhibition was observed against mutant NRAS cells; moreover, it was able to decrease tumour growth in MDA-MB-231 (KRAS-G13D) and PDTALL22 (NRAS-G13V) xenograft mouse models." (PMID 32770300, 2020). "The most obvious reason to consider the plausibility of NRAS gain-of-function being capable of driving chromaffin tumour development is that increased RAS signalling serves as a convergence point for the perturbed signal-transducing processes of RTK/RAS-driven PPGLs." (PMID 33138083, 2020). "Molecular analysis of primary tumor tissues revealed the following RAS mutations: KRAS G12D (two cases); KRAS G12V (three cases); KRAS G12C (three cases); KRAS G13D (one case); NRAS G12D (one case); NRAS A146T (one case); NRAS Q61R (one case)." (PMID 33291569, 2020). "In our cohort, 28 of 83 (34%) patients had BRAF V600Mx, KRAS Mx, NRAS G12/G13 and/or NRAS Q61 mutations in their bone marrow tumor DNA sample (4 [5%] BRAF V600Mx mutations, 13 [16%] KRAS Mx mutations, 3 [4%] NRAS G12/G13 mutations, 14 [17%] NRAS Q61 mutations)." (PMID 32284750, 2020). "Among the significant prognosticators, NRAS mutations (p = 0.03), M1c stage (p = 0.0016), presence of brain metastases (p = 0.0001), high LDH levels (p = 0.0002), and elevated tumor burden (p = 0.01) resulted in a significant correlation with poor outcome in univariate analysis." (PMID 32731406, 2020). "As for clinicopathological factors, methylation phenotypes of MM did not associate with genetic mutations, such as BRAF and NRAS, age, tumor site, or the presence of ulcers." (PMID 32406600, 2020). "Subgroup analysis of tumor DNA results showed that the median survival of patients with NRAS G12/G13 mutations was shorter than that of patients without NRAS G12/G13 mutations (9.6 months vs. 59 months, P=0.0201)." (PMID 32284750, 2020). "Forty one patients with baseline LB sample presented archival tumor tissue mutated for KRAS, NRAS, or BRAF (68.3%), and 38/41 (92.6%) demonstrated concordant status for the expected patient specific mutations, as supported by more than one mutational event out of two replicates." (PMID 31355139, 2019). "At lower frequency, in NRAS mutant tumor such changes also observed (2/12,16.7%)." (PMID 31391014, 2019).
tumor (continued). "Of those, the NRAS c.182A > G variant (p.Q61R) was identified in 9/176 alleles (5%) of the tumor samples, while no mutant reads were detected in the leukocyte samples." (PMID 31511039, 2019). "Furthermore, circDLST was co-localized with miR-502-5p in the cytoplasm of GC cells, and acted as a sponge of miR-502-3p in GC cells, which abrogated the tumor promoting effects of circDLST by inactivating the NRAS/MEK1/ERK1/2 signaling in GC cells." (PMID 30953514, 2019). "Our data differ from those reported recently, according to which - based on the mutational status in the primary tumor - BRAF- and NRAS-mutant tumors more often develop metastasis to the CNS and liver and NRAS mutant tumors have been associated with lung metastasis." (PMID 31391014, 2019). "Subsequent comparisons of genomic profiles from an additional twelve LGSC cell models showed frequent deletion of Chr9p (including loss of MTAP and CDKN2A genes) and oncogenic mutations in KRAS and NRAS genes, in agreement with results from previous studies on LGSC tumor tissues." (PMID 30636931, 2019). "Interestingly, the top predictions from genomic data across tumor types were all MEK inhibitors (PD0325901, selumetinib, and trametinib), which were associated with BRAF and KRAS/NRAS mutations." (PMID 31253656, 2019). "It is worth noting that although this tumor was progressing on the PD1 inhibitor pembrolizumab, this patient had progressed on prior BRAF/MEK inhibitor combination therapy, presumably due to the activating NRAS Q22K mutation." (PMID 31795494, 2019). "In this study, the oncogenic impact of four non-canonical/novel KRAS and NRAS mutations identified from malignant CRC tumor samples were investigated." (PMID 31816869, 2019). "An NRAS G12D mutant tumour also showed cetuximab resistance." (PMID 31653970, 2019). "In contrast, KRAS and NRAS mutations have not been detected in tumour biopsy from patients that progressed following treatment with first-generation TKIs." (PMID 30857358, 2019). "Interestingly, in one case (patient F), NRAS mutation was detected in liquid biopsy at diagnosis of tumor recurrence, while the NGS analysis of primary tumor tissue resulted in RAS wild type." (PMID 31597339, 2019). "There were 6 tumors with coexisting mutations of the same gene (1 with 2 BRAF, 2 with 2 NRAS, 1 with 2 PIK3CA, 1 with 2 KIT, and 1 with 3 KIT mutations), and 26 tumors with coexisting mutations of different genes, including a tumor with 2 NRAS and one PIK3CA mutation." (PMID 31277584, 2019). "In particular, they observed a statistically significant greater burden of missense mutations among men, even after adjusting for age at diagnosis, primary tumor site, stage at diagnosis, site of sequenced tumor, history of neoadjuvant treatment, and BRAF and NRAS mutation status." (PMID 29371600, 2018). "The precise role of BRAF and NRAS mutations in tumour progression has not yet been definitively established." (PMID 29755118, 2018). "In conclusion, this study demonstrated that evaluation with the Idylla system of the BRAF and NRAS mutation status in cfDNA may be a surrogate for determination of the BRAF and NRAS status in tumor tissue." (PMID 30546839, 2018). "Further, treatment of NRAS-mutant tumor-bearing mice with 6-thio-dG slowed the growth of tumors." (PMID 29695835, 2018). "Moreover, our analysis identifies consistent cross-cancer effects for 4 genes (FGFR1, ERRB2, IDH1, KRAS/NRAS) in 11 histological tumor types." (PMID 30442178, 2018). "Furthermore, disrupting ptprκ in zebrafish bolsters melanomagenesis by NRAS, consistent with its assigned tumor suppressor role." (PMID 30185827, 2018).